HIF1A (hypoxia inducible factor 1 subunit alpha)
Diseases named in the same sentence as HIF1A in open-access papers (continued):
Sharing a sentence is not in itself a finding about the gene and the disease.
tumor (continued). "Tumor hypoxia induced 4E-BP1, decreases cap-dependent translation and activates cap-independent translation of mRNAs encoding HIF1α and VEGFA, which contributes to cell survival and angiogenesis." (PMID 26204490, 2015). "Clinically, HIF-1α overexpression has been correlated with tumor grade, metastasis, and poor prognostic outcomes in many types of cancers." (PMID 25821081, 2015). "We also observed CAIX staining in 518A2 xenografts in many nested tumor regions, preferable near necrotic areas co-localized with HIF1α." (PMID 25997619, 2015). "LOX is involved in the hypoxic upregulation of HIF1A, and LOX and HIF-1α potentiate each other to foster tumor progression in the colon through the PI3K-Akt signaling pathway." (PMID 25790191, 2015). "All of these phenomena are related to the complex tumor microenvironment, as many of its components, such as IL-6, HIF-1α, and TGF-β, are concerned with induction and maintenance of CSCs." (PMID 26705466, 2015). "The tumor suppressor VHL is an E3 ubiquitin ligase responsible for regulating the degradation of hypoxia-inducible factor 1α (HIF-1α)." (PMID 26474388, 2015). "VEGF is a key proangiogenic activator which can be induced at transcriptional level by HIF-1α, and well known to play an important role in tumor growth and angiogenesis." (PMID 26388612, 2015). "Our study suggests that downstream signaling from IGFI to HIF1α, which has been the target of many insulin signaling drugs in clinical trials, plays a smaller role in overall tumor growth." (PMID 25884993, 2015). "Intriguingly, we found a correlation between EGF treatment and miR-622 reduction under hypoxia, which led to an elevated HIF-1α level and promoted tumor cell invasion." (PMID 26528854, 2015). "HIF1α has a central role in regulating a broad spectrum of genes involved in tumor angiogenesis, invasion, and metastasis." (PMID 26623560, 2015). "Many molecule mechanisms, especially VE-cadherin, EphA2, PI3K, MMPs, VEGFR1 and HIF-1a, are involved in tumour migration, invasion, and VM formation." (PMID 25598425, 2015). "All of these pathways play critical roles in tumor progression by modulating HIF-1α synthesis, cell migration and invasion." (PMID 26047481, 2015). "Western blot analysis on tumor lysates collected at Day 5 confirmed the marked decrease of HIF-1α protein expression when animals were treated with anti-S1P mAb in all samples examined." (PMID 25915662, 2015). "In fact, many studies have indicated that HIF1A functions as a tumor suppressor instead of a tumor promoter in many cancers." (PMID 26432836, 2015). "Hypoxia-inducible factor-1 (HIF-1) is a critical regulator of the tumor cell response to hypoxia, and it consists of an oxygen-dependent α-subunit (HIF-1α) and an oxygen-independent β-subunit (HIF-1β)." (PMID 25941936, 2015). "Previous studies have determined that GPER contributes together with HIF-1α to the adaptive responses to hypoxic tumor microenvironment." (PMID 26415222, 2015). "Consistent with this notion, tumor hypoxia correlates with overexpression of HIF-1α, and consequently with TWIST and Snail expression." (PMID 26520789, 2015). "In this sense melatonin has been described to decrease invasion and cell migration by blocking HIF-1α in some tumor types." (PMID 26252771, 2015). "Although these findings are reminiscent of previous reports that HIF-1α retards tumor growth, our data collectively indicate that HIF-1α has pleotropic effects that are context dependent." (PMID 25893706, 2015). "Hypoxia-inducible factor-1α (HIF-1α) is a key regulator for tumor cells and tissues to adapt to hypoxic condition." (PMID 25816356, 2015). "Increased expression of HIF-1α and HIF-2α has been detected in many different cancer types as well as in tumor-associated stromal cells, and, in both cases, high HIF levels are associated with a poor clinical outcome." (PMID 25085992, 2014).
tumor (continued). "In hypoxic conditions, reached when the tumor mass outgrows the available blood supply, resulting in areas of low oxygen tension, a more profound increase of HIF-1α protein levels is induced by the inhibition of its oxygen-dependent degradation." (PMID 25166211, 2014). "In order to exclude any influence of tumor dimension on HIF-1α expression, a correlation between these two parameters was performed without reaching any statistical significance (p = n.s)." (PMID 24902850, 2014). "Currently, YC-1 is also used as an inhibitor of hypoxia-inducible factor 1α (HIF-1α) to suppress the tumor growth." (PMID 24418169, 2014). "TGF-β1 and HIF-1α serve valuable functions in tumor angiogenesis and vascular remodeling, invasion and metastasis." (PMID 24669250, 2014). "Preclinical data have suggested that HIF-1α suppression can result in anticancer effects in several xenograft tumor models and delay of the initial growth in primary tumors and metastases as shown in a mouse model of breast cancer." (PMID 24732040, 2014). "We propose that DKG acts as a potent HIF-1α activator, highlighting the potential use of DKG to investigate the contribution of PHD2-HIF-1α pathway to tumor biology." (PMID 25420025, 2014). "The high proliferation of tumor cells can induce local hypoxia, which is a strong stimulus for HIF-1α." (PMID 24647137, 2014). "A previous study indicated that upregulation of miRNA-18a downregulates the expression level of HIF-1α in tumor tissues." (PMID 25371752, 2014). "A key event that initiates or enhances the angiogenic process is stabilization of hypoxia inducible factor 1-alpha (HIF1α) in the hypoxic tumor microenvironment." (PMID 24787299, 2014). "A previous study reported that mTOR, an important downstream target of PI3K/AKT, can also increase HIF-1α-dependent gene expression in certain tumor cell types." (PMID 24722367, 2014). "In general, activation of HIF1A and hypoxia-responsive genes puts tumor cells in a survival and invasive state with reduced proliferation." (PMID 25069832, 2014). "This appears to be a class effect as the proteasome inhibitors bortezomib and NPI-0052 have been shown in vitro to inhibit tumor angiogenesis as a result of decreased VEGF expression via downregulation of HIF-1α." (PMID 25373733, 2014). "Although the influences of HIF-1α on tumor cells have been widely studied, the role of HIF-1β expression in tumor cell survival have been reported in few literature and therefore remains to be investigated." (PMID 25068796, 2014). "Among the five patients with both pre- and post-dose tumor biopsies, four had positive HIF-1α staining at baseline." (PMID 25373733, 2014). "Upregulated expression of cMyc and HIF-1α in liver of DL mice further confirmed carcinogenic activity in hypoxic tumor microenvironment of liver of DL mice." (PMID 24932681, 2014). "HIF-1α is a master regulator of tumor angiogenesis, and SHARP1 inhibited VEGFA mRNA expression in our study." (PMID 24918449, 2014). "Taken together, these findings suggest a new role of the PH domain of PLD1 in tumor regression via targeting of HIF-1α." (PMID 25361009, 2014). "TRAF6 also upregulates the expression of hypoxia-inducible factor 1α (HIF-1α) to promote tumor angiogenesis." (PMID 25340740, 2014). "Since HIF-1α represents one of the main responsible for the metabolic switch from mitochondrial respiration to glycolysis (Warburg effect) in tumour cells, we analysed some HIF-1α -dependent genes, involved in these molecular pathways." (PMID 24804733, 2014). "The expression of HIF-1α in a hypoxemic tumor microenvironment changes the metabolism of glucose from aerobic to nonaerobic process." (PMID 24745019, 2014). "Overexpression of HIF-1α also downregulated miR-20b expression in normoxic tumour cells, whereas HIF-1α repression in hypoxic tumour cells caused miR-20b to increase." (PMID 25197665, 2014).
tumor (continued). "As a result of all this, HIF-1α is overexpressed in a variety of tumours, usually being a marker of poor prognosis, early recurrence and resistance to chemotherapy." (PMID 24835245, 2014). "Many studies have suggested the importance of increased HIF-1α levels in the tumorigenesis and progression of various cancers by promoting tumor angiogenesis and the development of other hallmarks of cancer." (PMID 25162518, 2014). "Levels of heat shock proteins HSP70 and HSP27 were higher for all individual samples for ablated (N=5) as compared to control (N=4) tumor tissue; whereas levels of hypoxia inducible factor (HIF-1α) were consistently lower for ablated tumors." (PMID 24270800, 2014). "It is possible that selective enrichment of infiltrating MDSC in HIF1A found in our study suggests tumor type-specific mechanisms of immune suppression." (PMID 25294811, 2014). "Further research is required to elucidate the net effect of using HIF-1α activators to boost TEFF cell-mediated responses to persistent tumor antigen challenge." (PMID 24904823, 2014). "As tumor growth outstrips its vasculature, resulting in a hypoxic microenvironment, activation of the HIF-1α/VEGF axis plays a critical role in initiating tumor angiogenesis and progression." (PMID 24918449, 2014). "Since hypoxia-induced angiogenesis is required for tumor growth, HIF1α is heavily involved in the development and progression of several types of human malignancies." (PMID 24567056, 2014). "Our data showed a low expression of HIF-1α in tumor cells and an almost total absence in the surrounding stroma." (PMID 25243117, 2014). "This mode of respiratory regulation has oncogenic implications, as the accumulation of succinate elicited by SDH inhibition stabilizes the transcription factor HIF1α and prompts tumor growth." (PMID 25564869, 2014). "Re-expression of miR-199a-5p impaired arsenic-induced angiogenesis and tumor growth through its direct targets HIF-1α and COX-2." (PMID 24413338, 2014). "CAIX expression at the cell surface in peri-necrotic tumor regions reflected the pattern of HIF-1α expression, a finding in agreement with previous studies." (PMID 25127378, 2014). "HIF-1α signaling plays a critical role in tumor metastasis, invasion, metabolism, and, especially, angiogenesis." (PMID 24413338, 2014). "In tumour spheroids, U87 cells showed an accumulation of HIF-1α substantially hydroxylated at both Pro402 and Pro564." (PMID 24563687, 2014). "Although TG2, HJURP, and HIF-1α have proven to be important predictors of radiosensitivity in a number of tumor types, their role in the evolution of CIS has yet to be investigated." (PMID 25243117, 2014). "In conclusion, our findings suggest that the increased expression of the PI3K/Akt or HIF-1α pathway is closely correlated with tumor differentiation, TNM staging, lymph node metastases, and lymphatic and vascular infiltration." (PMID 24765145, 2014). "Hypoxia inducible factor 1α (HIF-1α) is a master regulator of tumor angiogenesis being one of the major targets for cancer therapy." (PMID 25166596, 2014). "Overall, our findings indicate that the increased expression of the PI3K/Akt/HIF-1α pathway was closely correlated with tumor differentiation, TNM staging, lymph node metastases and lymphatic and vascular infiltration." (PMID 24765145, 2014). "Studies have shown that HIF-1α is expected to be an important indicator that contributes to predicting tumor diagnosis and recurrence, as well as in monitoring tumor invasion and metastasis." (PMID 25013467, 2014). "VEGF, an immediate downstream target gene of HIF-1α, plays a pivotal role in tumor angiogenesis, especially under conditions of intratumoral hypoxia." (PMID 25295523, 2014). "HIF-1α is a transcription factor that has been reported to control more than 60 genes and has been demonstrated to play an important role in tumor angiogenesis, metastasis, growth and chemoresistance." (PMID 25115400, 2014).
tumor (continued). "Ectopic HIF1A expression in MDA-MB-231 cells was previously reported to suppress tumor growth in a xenograft model." (PMID 25069832, 2014). "The model can also be used to monitor the change of pH, GSH and oxygen in tumor as a result of the absence or presence of macrophage HIFαs (HIF-1α or HIF-2α) and corresponding effectiveness of chemotherapeutic drugs." (PMID 25295611, 2014). "Because of its capability for increasing oxygen availability in tissues, Hif1α plays a fundamental role in tumor progression." (PMID 25126540, 2014). "Serum Ang-2 and MMP-2 and tumor HIF-1α were identified as relevant baseline biomarkers of sunitinib activity in advanced RCC, warranting further research into their prognostic versus predictive value." (PMID 25100134, 2014). "Conversely, in normoxia tissues, HIF-1α is modified by oxygen-sensitive prolyl hydroxylases and asparaginyl hydroxylase, making it recognisable by the tumour suppressor von Hippel Lindau protein, resulting in the suppression of CA-ΙΧ expression." (PMID 25547490, 2014). "HIF-1α evaluation showed a higher expression in both tumor and stromal cells in patients with relapsed G3 tumors, indicating a potential role of this marker in CIS evolution." (PMID 25243117, 2014). "The hypoxic microenvironment of tumor cells facilitates radio- and chemoresistance and the adaptation to hypoxia is regulated by HIF-1α." (PMID 25243117, 2014). "The mRNA expression of HIF-1α and cMyc was studied as an early response stress gene and oncogene respectively in hypoxic tumor microenvironment." (PMID 24932681, 2014). "Hypoxia is the key driver of CA-ΙΧ expression in tumour cells, and is induced by an HIF-1α-mediated signalling cascade." (PMID 25547490, 2014). "Activation of PI3K/Akt signaling promotes the progression of hepatocarcinogenesis, while its blockade controls angiogenesis and tumor growth by regulating the expression of HIF-1α." (PMID 24765145, 2014). "It has also been reported that the expression of HIF-1α in most tumor tissues was related to tumor invasion, metastasis and prognosis." (PMID 25089613, 2014). "In summary, we demonstrated that LCN2 levels increased in tumor cells cultured under hypoxic conditions, at HIF-1α-positive regions of tumors, and in plasma collected from mice bearing hypoxic tumors." (PMID 25467539, 2014). "Optimal choice of carrier type and drug payload will likely involve both identifying goals of treatment and prioritizing outcome metrics (e.g., local suppression of a specific cytokine such as HIF-1α or control of tumor growth)." (PMID 25133740, 2014). "HIF-1α, an essential factor in tumor progression, was up-regulated in SDHB-silenced cells with the activation of p-AMPKα and down-regulated in SDHB-overexpressed cancer cells with the decreased p-AMPKα." (PMID 25491408, 2014). "Low O2 tension of a growing tumor allows stabilization of HIF-1α, leading to increased VEGF-A transcription, which binds to VEGFR2." (PMID 24416386, 2014). "Overexpression of HIF-1α in tumor tissues has been shown to correlate with upregulation of vascular endothelial growth factor (VEGF), stimulating angiogenesis and poor prognosis." (PMID 25013467, 2014). "Overexpression of miR-519c resulted in a significant decrease of HIF-1-α and the reduction of tumor angiogenesis." (PMID 24744457, 2014). "It has been indicated that tumor necrosis factor receptor-associated factor-6 (TRAF6) will upregulate the expression of hypoxia-inducible factor-1α (HIF-1α) and promote tumor angiogenesis." (PMID 25089269, 2014). "Recently we showed that BT20 and MCF7 cells cultured as tumor spheroids on PDMS expressed HIF-1α and HIF-1β." (PMID 25343626, 2014). "When we examined virulent compared with attenuated T. annulata-infected macrophages we expected to find reduced HIF-1α levels, since HIF-1α activation is frequently associated with aggressive tumours and poor prognosis." (PMID 24112286, 2014).
tumor (continued). "For instance, hypoxic stress in the tumor microenvironment evokes Ape/Ref-1 to facilitate the DNA binding activity of HIF-1α, triggering the expression of downstream genes including vascular endothelial growth factor (VEGF), miR210, and CA-9." (PMID 24416428, 2014). "Tumours are able to stabilise the proline-hydroxylated form of HIF-1α, providing another mechanism for regulating HIF in cancer." (PMID 24563687, 2014). "Hypoxia inducible factor 1α (HIF-1α) is a stress-responsive transcription factor to hypoxia and its expression is correlated to tumor progression and angiogenesis." (PMID 25302049, 2014). "The downstream targets of hypoxia inducible factor-1 alpha (HIF-1α) play an important role in tumor progression and angiogenesis." (PMID 24775564, 2014). "In this study, we demonstrated the effects of silencing HIF-1β expression on HCC cells, and found that HIF-1β-silencing regulates dimerization with HIF-1α under hypoxic conditions, leading to the suppression of tumor cell growth, invasion, and migration." (PMID 25068796, 2014). "Existing literature confirmed that flavonoids can inhibit glycolytic enzymes (such as HIF-1α) activity that affect the metabolism of tumor cells and promote apoptosis of tumor cells." (PMID 24976852, 2014). "Consistent data highlight the role of macrophage-derived-HIF1α in generating a localized immune privileged site within the tumor milieu via iNOS and ARG1 induction." (PMID 24605112, 2014). "One mechanism of tumor resistance to anti-angiogenic therapy is upregulation of the transcription factor hypoxia-inducible factor 1α (HIF-1α), which mediates adaptive responses to hypoxic conditions commonly found in solid tumors." (PMID 25373733, 2014). "Previous studies have indicated that TGF-β1 and HIF-1α promote angiogenesis through the TGF-β1/PHD2/HIF-1α/VEGF pathway in the process of tumor angiogenesis." (PMID 24669250, 2014). "Pharmacodynamic assessment included plasma VEGF, VEGFR2, 20S proteasome inhibition, dynamic contrast-enhanced magnetic resonance imaging (DCE-MRI), and HIF-1α tumor expression." (PMID 25373733, 2014). "This study thus functionally linked OATPs with hypoxia/HIF-1α signaling in the canine cancer model system, providing mechanistic insights for NIR fluorescence tumor imaging." (PMID 25361418, 2014). "This work represents the first link between the functional ablation of Rb in tumor cells and HIF1α-dependent transcriptional activation and invasion." (PMID 24919196, 2014). "We simulated the effects of a reoxygenation after a hypoxic event, and we plotted the evolution of total HiF-1α for = 1000 (normal cells) and 5000 (tumor cells)." (PMID 25338163, 2014). "In hypoxic tumors expressing HIF-1α, we observed that many macrophages invaded into the tumor tissue." (PMID 25467539, 2014). "JMJD1A has been well documented to induce tumor progression by up-regulating HIF1α expression and stimulating angiogenesis." (PMID 24742640, 2014). "HIF-1α plays a major role in several aspects of tumor biology, such as glucose uptake, metabolism, growth rate, angiogenesis, invasiveness, metastasis and apoptosis." (PMID 25377659, 2014). "Chaivarina and colleagues stably-expressed HIF-1α in fibroblasts and found a 3-fold increase in tumor volume, indicating a relation between CAFs, hypoxia and tumor progression." (PMID 24978438, 2014). "With the tropisms of HIF-1α on proliferation, migration, and invasion, its activation would be consequential to tumor growth and metastasis." (PMID 24668884, 2014). "In this study, we aimed to determine if proline-hydroxylated HIF-1α formed a component of upregulated HIF-1α expressed in vivo in tumours." (PMID 24563687, 2014). "Erk1-2 in turn promotes the activation of mTOR signaling, known to regulate HIF-1α protein translation and tumor growth." (PMID 25166211, 2014). "Previous studies have shown that Histone Deacetylase Inhibitors (HDACi) block tumor angiogenesis through the inhibition of HIF-1α expression." (PMID 25166596, 2014).